KRT7-AS (KRT7 antisense RNA 1)
Gene: Long non-coding RNA gene on chromosome 12 (52,245,048 to 52,247,448, reverse strand). Ensembl gene ENSG00000257671.
Diseases named in the same sentence as KRT7-AS in open-access papers:
KRT7-AS is named in the same sentence as 1 disease in open-access papers, as found by Europe PMC text mining. Sharing a sentence is not in itself a finding about the gene and the disease. The quoted sentences say what the papers report.
cancer (2 papers, 2023). A tumor composed of atypical neoplastic, often pleomorphic cells that invade other tissues. "On the other hand, overexpression of KRT7-AS (by small molecule berberine) inhibits tumorigenesis and sensitizes cancer cells to platamin, an anti-cancer drug." (PMID 38260844, 2023). "Thus, KRT7-AS and berberine are potential cancer candidates for the development of novel therapeutics against cancers." (PMID 37185462, 2023).